MTOR (mechanistic target of rapamycin kinase)
Diseases named in the same sentence as MTOR in open-access papers (continued):
Sharing a sentence is not in itself a finding about the gene and the disease.
triple-negative breast carcinoma (continued). "Combination of everolimus also known as RAD001 (oral mammalian target of rapamycin (mTOR) inhibitor) and carboplatin may have activity in metastatic triple-negative breast cancer (TNBC)." (PMID 24684785, 2014). "Furthermore, several studies have demonstrated that PI3Kca mutation resulted in the persistent activation of the PI3K/AKT/mTOR signaling pathway and inhibition of programmed cell death, thereby facilitating the development of resistance to chemotherapy in triple-negative breast cancer." (PMID 39539450, 2024). "Furthermore, fluphenazine hydrochloride is also able to decrease the expression of p44/42 ERK and phosphorylate AKT, involved in the RAS/RAF/MEK/ERK and PI3K/AKT/mTOR pathways, relevant for triple-negative breast cancer, resulting in the suppression of the growth and survival of cancer cells." (PMID 36983018, 2023). "Targeted therapy with mTOR inhibitors may be beneficial in treating triple-negative breast cancer." (PMID 36299777, 2022). "Moreover, our research found that tetrandrine was also an inhibitor of PI3K/AKT/mTOR signaling pathway and could significantly inhibit the proliferation and induce apoptosis in triple-negative breast cancer MDA-MB-231 cells." (PMID 30713576, 2019). "GBP2 enhances paclitaxel sensitivity in triple-negative breast cancer by promoting autophagy in combination with ATG2 and inhibiting the PI3K/AKT/mTOR pathway." (PMID 41007849, 2025). "Prior to the clinical application of mTOR inhibitors for antitumour effects, phase III trials assessing their potential against triple-negative breast cancer are warranted." (PMID 38734930, 2024). "Firstly, B7-H3 affects tumor cell metabolism, as evidenced in triple-negative breast cancer where decreased B7-H3 expression reduces tumor cell glycolytic capacity and increases sensitivity to AKT/mTOR inhibitors." (PMID 38468228, 2024). "Further in vitro experiments also found that Z8 has a low EC50 and can inhibit the malignant biological behaviors of KK-LC-1 high expressed triple-negative breast cancer cells MDA-MB-231 and MDA-MB-468 by MAL2/MUC1-C/PI3K/AKT/mTOR pathway." (PMID 36895039, 2023). "To further explore if Z8 can also influence the pathway of MAL2/MUC1-C/PI3K/AKT/mTOR, we treatment MDA-MB-231 and MDA-MB-468 triple-negative breast cancer cell lines with Z839878730." (PMID 36895039, 2023). "AS a carcinogenic lncRNA in triple-negative breast cancer, NAMPT-AS/NAMPT promotes the progression of tumors and metastasis by regulating autophagy by the mTOR pathway." (PMID 35813295, 2022). "Similar views were also found in a previous report that LTF inhibited cell growth of highly metastatic triple-negative breast cancer cell lines MDA-MB231 and Hs578t via suppressing the mTOR activity." (PMID 34944711, 2021). "It was recently shown that mTOR inhibitors impair homologous recombination repair and synergize with PARP inhibitors through a negative regulation of SUV39H1 in BRCA-proficient triple-negative breast cancer cell lines." (PMID 30038706, 2018). "Similarly, in murine models of triple-negative breast cancer, the dual PI3K/mTOR inhibitor gedatolisib has been shown to significantly enhance ICIs’ efficacy, resulting in robust tumor growth inhibition and the activation of anti-tumor immune responses." (PMID 40649958, 2025). "In triple-negative breast cancer, the TIGIT/CD155 pathway was also found to inhibit PI3K, p-AKT, and p-mTOR expression, reducing glucose uptake and lactic acid production in CD8+ T cells, leading to CD8+ T cell activation and impairment of effector functions in the tumor microenvironment." (PMID 41024301, 2025).
triple-negative breast carcinoma (continued). "Furthermore, as we all know, mTOR is a negative regulator of autophagy, and SFN decreased the phosphorylation level of mTOR, leading to autophagy induction in triple-negative breast cancer cells (TNBCs)." (PMID 37190316, 2023). "Overactivation of mTOR also commonly occurs in multiple cancer types, some studies revealed that Aur-A/ERK1/2/mTOR formed an oncogenic cascade in triple-negative breast cancer (TNBC), and double inhibition of Aur-A and mTOR showed significant synergistic effects in TNBC models." (PMID 35831273, 2022). "This is further supported by a more recent study, showing that M2 TAMs augment triple negative breast cancer growth and promote angiogenesis via vascular endothelial growth factor (VEGF)/acutely transforming retrovirus (AKT)/mammalian target of rapamycin (mTOR) signalling pathway." (PMID 36483045, 2022). "On the basis of our data, the treatment of triple negative breast cancer in a non-metastatic stage with an AKT1/2 inhibitor in combination with other established drugs or mTOR inhibitors like RAD001 should be taken forward in further studies." (PMID 33670586, 2021). "Hence, the combination of therapy against mTOR and STAT3 is a promising prospect for the treatment of triple negative breast cancer." (PMID 32669950, 2020). "Therefore, tetrandrine inhibited the triple-negative breast cancer MDA-MB-231 cell proliferation and induced autophagy likely by the inhibition of PI3K/AKT/mTOR signaling pathway." (PMID 30713576, 2019). "The triple-negative breast cancer MDA-MB-231 cells autophagy induced by tetrandrine was by inhibiting the PI3K/AKT/mTOR signaling via upregulating PTEN expression and downregulating p-akt ser473 /akt, p-PI3K/PI3K p110α, p-mTOR ser2448 /mTOR." (PMID 30713576, 2019). "Uenget al. reported that p-mTOR expression is an adverse prognostic indicator in early-stage (stage I and II) triple negative breast cancer, whereas it is not statistically significant in patients with stage III and IV." (PMID 28114374, 2017). "We have searched trials using Medline (PUBMED), EMBASE and COCHRAINE database, the following search strategy (“TNBC” [MESH] AND (“PI3K” [tiab] OR “mTOR” [tiab]) AND (“ER” [tiab] OR “PgR” [tiab]) and free text terms as “PI3K” [tiab], “triple negative breast cancer” [tiab] and “mTOR” [tiab]." (PMID 27474173, 2016). "We chose four everolimus resistant triple-negative breast cancer cell lines, MDA-MB-231, MDA-MB-436, BT20 and HCC1143, characterized by a diversity of activated signaling pathways and proliferation inhibition by ATP competitive inhibitors to mTOR." (PMID 26148118, 2015). "Distinctly, under conditions of metabolic and oxidative stress in triple negative breast cancers, we found that mTORC2 activation leads to elevated ATF4 expression, overall suggesting that ATF4 could serve as a biomarker for treatment with mTOR inhibitors in some cancers." (PMID 35963851, 2022). "However, it is unclear whether tetrandrine can induce autophagy in triple-negative breast cancer cells and whether its mechanism inhibits PI3K/AKT/mTOR pathway." (PMID 30713576, 2019). "In a low percentage of triple-negative breast cancers, PI3K/AKT/mTOR pathway is activated, which lead to the hypothesis that inhibition of the PI3K signaling pathway may ensure a proper treatment for patients diagnosed with mesenchymal and luminal androgen receptor (LAR) types of TNBCs." (PMID 28445140, 2017). "A phase II nonrandamized study with triple negative breast cancer patients is currently evaluating the temsirolimus, an intravenous mTOR inhibitor and a phase III randamized study with a neoadjuvant setting is currently evaluating everolimus in combination with antracyclines and taxanes." (PMID 29147345, 2013).
triple-negative breast carcinoma (continued). "This study aimed to investigate the safety and efficacy of the combination of an mTOR/pan-PI3K inhibitor, gedatolisib, with the PARP inhibitor, talazoparib, in patients with advanced triple negative breast cancer or advanced HER2 negative breast cancer and a germline BRCA1/2 mutation." (PMID 40471518, 2025).
viral infection (156 papers, 2012 to 2026). "Stresses such as nutrient deprivation, viral infection, oxidative damage, and endoplasmic reticulum (ER) stress cause phosphorylation of eukaryotic initiation factor-2α (eIF2α) or inhibition of mammalian target of rapamycin (mTOR) signaling." (PMID 41226581, 2025). "After the EV71 virus attaches and enters the host cell, it activates the PI3K/Akt/mTOR signaling pathway, reduces the apoptosis of host cells caused by virus infection, and enables the virus to continue to infect cells." (PMID 36014530, 2022). "The association between the use of mTOR inhibitors and reduced rates of viral infections has been shown in several studies, including a recent meta-analysis in kidney transplant recipients." (PMID 28716027, 2017). "Since the most common tumours that develop in transplant recipients are virally associated, how do mTOR inhibitors influence specific viral infections in these patients?" (PMID 24565200, 2013). "Viral infection-related pathways, such as Kaposi sarcoma-associated herpesvirus infection (hsa05167; FE = 58.97) and human cytomegalovirus infection (hsa05163; FE = 40.86), were enriched with MTOR, NFκβ1, STAT3, and CASP3." (PMID 41011481, 2025). "With respect to the first hypothesis, we underline that a potential positive impact of mTOR inhibitors in the course of several viral infections is already known in the literature." (PMID 35801204, 2022). "However, the risk of viral infections (cytomegalovirus and BK) was significantly less with mTOR combined with everolimus." (PMID 32192172, 2020). "Mammalian target of rapamycin (mTOR) inhibitors are currently considered an alternative immunosuppressive treatment that can prevent the nephrotoxicity, viral infections and malignancies that are associated with calcineurin inhibitor-based immunosuppressive regimens." (PMID 24565231, 2013). "Thus, we hypothesized that the activity of the mTOR pathway is associated with virus infections like BKPyV and HCMV in renal transplant recipients." (PMID 33800846, 2021). "Inhibiting the mammalian target of rapamycin (mTOR) during acute viral infection generates highly functional memory CD8+ T cells." (PMID 42024459, 2026). "The TRANSFORM study found fewer viral infections in the mTOR group compared to mycophenolate (17.2% vs. 29.2%, p < 0.001)." (PMID 40872883, 2025). "Viral infection inhibits mTOR and CDK1 phosphorylation, which enhances LARP1’s binding to viral RNA and inhibits viral translation." (PMID 40294010, 2025). "mTOR is an important autophagy regulatory protein and regulates a variety of downstream transcription factors; many viral infections activate the mTOR pathway." (PMID 41156741, 2025). "In contrast, CONF-specific genes were enriched in only six pathways, mainly viral infections and mTOR signaling." (PMID 41036197, 2025). "Our findings are consistent with severalpreviously published studies investigating the impact of mTOR inhibitors on viral infections." (PMID 40978637, 2025). "The activation of signaling pathways, such as the mTOR pathway, in response to viral infection, serves as an illustrative example of a common theme." (PMID 39766256, 2024). "In Delta, the mTOR pathway was observed to regulate ribosome biogenesis, autophagy, and lipid biosynthesis while also playing a role in viral infection pathways." (PMID 39717902, 2024). "C) Certain signaling pathways that are activated during viral infections, such as mTOR or immune-related pathways, play a role in the response to different viral infections, including hepatitis B, resulting in concurrent pathway activation." (PMID 39766256, 2024). "In the Japanese flounder, pten and its regulatory miRNAs modulate autophagic cell activation via the AKT/mTOR pathway during bacterial and viral infections, inducing apoptosis." (PMID 39456653, 2024).
viral infection (continued). "Metabolic stress and inflammation significantly contribute to β-cell dedifferentiation and transdifferentiation by dysregulating various pathways, including ER stress, the mTOR pathway, the endocannabinoid system, viral infections, and aging." (PMID 39057094, 2024). "AKT is one of the critical signaling molecules regulating mTORC1 activity, and some virus infections activate the AKT/mTOR pathway to enhance the viral protein expression, including JC polyomavirus (JCPyV), human cytomegalovirus (HCMV), and MERS-CoV." (PMID 39000284, 2024). "Viral infection can trigger the activation of the PI3K/Akt/mTOR and NF-κB signaling pathways, which benefits viral infection and replication by reducing cell apoptosis, and induces inflammatory cytokines expression." (PMID 37954857, 2023). "Previous studies showed that mTOR inhibitors (sirolimus and everolimus) reduce the incidence of viral diseases, including CMV infections." (PMID 37111407, 2023). "In summary, investigating the effect of autophagy induction via the PI3K/AKT/mTOR pathway on viral replication can improve our comprehension of viral infection mechanisms and provide a foundation for the creation of new antiviral approaches." (PMID 38125906, 2023). "The important role of mTOR in innate immunity inextricably links the PI3K-AKT-mTOR pathway to viral infection." (PMID 37162335, 2023). "Both pathways are critical in the control of mTOR signalling that governs cell proliferation and metabolism and have been shown to be modulated by viral infections to support viral replication." (PMID 37055751, 2023). "We further investigate the interaction between mTOR and Rheb in the context of viral infection using a coimmunoprecipitation assay." (PMID 36735752, 2023). "Dysregulated signaling pathways were also identified, including the mTOR signaling pathway, cardiomyopathy pathway, COVID-19 signaling pathway, and pathways involved in bacterial or viral infection." (PMID 37841239, 2023). "During acute FV infection, NK cells increase their cytokine production and release, indicating an important function of mTOR during acute virus infections." (PMID 38094304, 2023). "Several studies have shown that viral infection can increase viral replication by activating the PI3K/AKT/mTOR pathway, thereby accessing additional cellular resources." (PMID 38125906, 2023). "Several reports had shown that mTOR inhibitors with low-dose CNI reduce the incidence of infection, particularly the risk of viral infections including CMV and BKV." (PMID 38105889, 2023). "Our rapamycin treatment data clearly show that mTOR plays a crucial role in T cell responses during chronic viral infection." (PMID 36378537, 2023). "Here, we showed that mTOR inhibition has distinct outcomes during the beginning of and after the establishment of chronic viral infection." (PMID 36378537, 2023). "It was reported that the Akt/mTOR pathway was required for eukaryotic translation initiation factor 4E (eIF4E) assembly and viral protein synthesis during virus infection." (PMID 35847100, 2022). "WSSV infection can also use the PI3K-Akt-mTOR-HIF1α pathway to induce lipid biosynthesis at 24 h post-viral infection to support WSSV morphogenesis." (PMID 36067252, 2022). "The applications of ATP-competitive inhibitors in central nervous system diseases, viral infections and inflammation have laid the foundation for expanding the indications of mTOR inhibitors." (PMID 36014530, 2022). "KEGG Enrichment analysis indicated that tRF‐31‐79MP9P9NH57SD was enriched in virus infection, a variety of tumors and mTOR signaling pathway." (PMID 35576497, 2022). "The predicted targets of DEmiRNAs were mainly enriched in the Wnt signaling pathway, phagosome, and mTOR signaling pathway, which are related to the virus infection." (PMID 36680059, 2022).
viral infection (continued). "The mTOR complex is a major player in the regulation of cellular metabolism and translation, and viral infection often triggers a cellular stress response that inactivates mTOR and, consequently, leads to a global downregulation of mRNA translation." (PMID 35458509, 2022). "The mTOR pathway is not only involved in cell metabolism and cell proliferation, as initially thought, but also related to immunity against bacterial and viral infection, including H. pylori infection." (PMID 34913612, 2022). "A great deal of evidence supports the notion that the mTOR signaling pathway plays an important role in viral infection, replication, particle assembly and release." (PMID 34367129, 2021). "To better describe molecular events underlying mTOR activation downstream of TBK1, we sought to determine how TBK1 engages with mTOR during viral infection." (PMID 33411856, 2021). "In virus infections, the inhibition of mTOR, a kinase involved in several biological processes, improves the response of memory CD8+ T-cells." (PMID 34123875, 2021). "The mTOR pathways contribute to cellular survival under conditions of stress including metabolic stress, which is posed by virus infections such as the fast replicating CVB3-EGFP." (PMID 33513663, 2021). "KEGG analysis revealed that metabolic pathway, viral infection, and oncogenesis have crucial roles in the pathogenesis of DM, while Wnt signaling and mTOR signaling were indicated to contribute to the pathogenesis in the ILD subset." (PMID 34368354, 2021). "Other viral proteins have also been implicated in the pathogenesis of virus infection; for example, ZIKV-NS4A and ZIKV-NS4B cooperatively suppressed the Akt-mTOR pathway to inhibit neurogenesis and induce autophagy in human fetal neural stem cell." (PMID 33610792, 2021). "Recently, it has been identified that the SARS-CoV-2 virus exploits the mTOR-signaling pathway to progress the infection; however, mTOR inhibitors suppress virus infection at a significant level with nanomolar concentrations." (PMID 34179893, 2021). "In our series, the lack of statistically significant differences between both no virus- and virus-related PHCC and HCC and between both HCV- and HBV-related PHCC and HCC seems to indicate an independent role of virus infection in the mTOR mRNA expression." (PMID 33362215, 2020). "When all tissues were considered according to the presence (Virus) or absence (Virus-) of viral infection, mTOR gene expression was significantly higher in both Virus HCC (58.3±44) and Virus- HCC (47.0±33) than in M (q = 0.01 and q = 0.04 respectively)." (PMID 33362215, 2020). "Here, we also found that EZH2 is indispensable for mTOR signal activation in CD4 T cells during acute viral infection." (PMID 32999031, 2020). "Although mTOR inhibitors have been used for enhancing protection against some bacterial and viral infections, and very recently in the treatment of cutaneous leishmaniasis, nothing is known about their effect in a vaccination protocol against VL." (PMID 32517744, 2020). "This pathway is pivotal in host immune response to virus infection, and is closely related to other pathways, such as Wnt signaling pathway, Toll-like receptor signaling pathway, mTOR signaling pathway and JAK-STAT signaling pathway." (PMID 32903522, 2020). "Together, these results indicated that impaired mTOR activity contributes to the poor expansion of virus-specific CD4 T cells devoid of EZH2 protein upon viral infection." (PMID 32999031, 2020). "In vivo, antiviral T-cell responses can be reduced by mTOR inhibitors, which also makes viral infections more effective." (PMID 32631270, 2020).